MMP2 (matrix metallopeptidase 2)
Diseases named in the same sentence as MMP2 in open-access papers (continued):
Sharing a sentence is not in itself a finding about the gene and the disease.
chondrosarcoma (36 papers, 2008 to 2026). A malignant cartilaginous matrix-producing mesenchymal neoplasm arising from the bone and soft tissue. "In summary, higher expressions of SphK1 and TIMP‐3 as well as lower expressions of miR‐101 and MMP‐2 were linked with chondrosarcoma development and metastasis." (PMID 28672103, 2017). "Taken together, high expressions of resistin and MMP-2, as well as reduced expression of miR-519d, were found to be associated with chondrosarcoma development and metastasis." (PMID 25404641, 2015). "It has been shown that the restoration of miR-145 expression by lentiviral transfection results in the downregulation of SOX9, ETV5, and MMP-2, leading to the reduced invasion and metastasis of Chondrosarcoma cells." (PMID 40429954, 2025). "In the case of MMP-2, most reports suggest that a higher expression of this enzyme was observed in chondrosarcoma of a higher histologic grade and in recurrent tumors." (PMID 38138968, 2023). "We have previously reported that NGF promotes MMP-2 expression and chondrosarcoma cell migration by inhibiting miR-423-5p expression through the FAK and c-Src signaling cascades." (PMID 34815382, 2021). "Visfatin-induced stimulation of MMP-2 synthesis and activation of the AP-1 transcription factor facilitated chondrosarcoma cell migration via the ERK, p38, and JNK signaling pathways." (PMID 34445345, 2021). "Visfatin also facilitates the migration of human chondrosarcoma cells through AP-1-dependent MMP-2 production in MAPK signaling pathways." (PMID 34445345, 2021). "In previous IHC tissue array investigations, we have documented higher levels of NGF and MMP-2 expression in patients with higher-grade chondrosarcoma than in those with lower-grade disease." (PMID 34815382, 2021). "In conclusion, our study identified that NGF promoted the MMP-2-dependent cell migration in human chondrosarcoma tissue by inhibiting the miR-423-5p synthesis via the FAK and c-Src signaling cascades." (PMID 34283074, 2021). "The transfection of cells with MMP-2 siRNA diminished the NGF-induced promotion of migration, implying that MMP-2 was critical to NGF-induced chondrosarcoma cell migration." (PMID 34283074, 2021). "Confirmation of these effects by genetic inhibition using c-Jun siRNA indicate that AP-1 transcriptional activation is involved in the effects of visfatin upon MMP-2 expression and chondrosarcoma cell migration." (PMID 34445345, 2021). "Here, we found that the levels of NGF and matrix metalloproteinase-2 (MMP-2) correlated with the tumor stage in patients with a chondrosarcoma." (PMID 34283074, 2021). "We also confirmed that NGF facilitates MMP-2-dependent chondrosarcoma cell migration and metastasis by inhibiting the miR-423-5p synthesis via FAK/c-Src signaling." (PMID 34283074, 2021). "We identified that NGF induces the MMP-2 synthesis and chondrosarcoma cell motility by inhibiting miR-423-5p expression through the FAK and c-Src pathways." (PMID 34283074, 2021). "Our results show that visfatin promotes the phosphorylation of ERK, p38, and JNK, while their respective pharmacological inhibitors suppress visfatin-induced promotion of MMP-2 expression and chondrosarcoma cell migration." (PMID 34445345, 2021). "In conclusion, our study has identified that visfatin facilitates the metastatic potential of chondrosarcoma cells via AP-1-dependent MMP-2 production in the ERK, p38, and JNK pathway." (PMID 34445345, 2021). "This evidence reveals that activation of ERK, p38, and JNK signaling controls visfatin-enhanced promotion of MMP-2 synthesis and migration of chondrosarcoma cells." (PMID 34445345, 2021). "We also confirmed that visfatin facilitates chondrosarcoma cell migration through AP-1-dependent MMP-2 expression in the MAPK signaling pathway." (PMID 34445345, 2021).
chondrosarcoma (continued). "We also observed that overexpression of visfatin facilitated increases in MMP-2 synthesis and chondrosarcoma metastasis in vitro and in vivo, leading us to believe that visfatin promotes chondrosarcoma metastasis via the upregulation of MMP-2." (PMID 34445345, 2021). "Our investigation has found that levels of NGF and MMP-2 expression are positively correlated with the tumor staging in patients with a chondrosarcoma." (PMID 34283074, 2021). "Transfecting the cells with MMP-2 siRNA diminished visfatin-induced promotion of cellular migration, implying that MMP-2 is critical to the effects of visfatin upon chondrosarcoma cells." (PMID 34445345, 2021). "Elevated MMP-2 levels are apparent in numerous tumor metastatic processes and MMP-2 reportedly mediates chondrosarcoma metastasis." (PMID 34445345, 2021). "Treating cells with a FAK inhibitor diminished the NGF-induced c-Src phosphorylation indicating that the FAK/c-Src signaling cascade regulated the NGF-induced MMP-2 synthesis and chondrosarcoma cell migration." (PMID 34283074, 2021). "NGF facilitated the MMP-2-dependent cellular migration in human chondrosarcoma JJ012 cells while the overexpression of NGF enhanced the lung metastasis in a mouse model of a chondrosarcoma." (PMID 34283074, 2021). "Not only have significantly higher levels of MMP-2 production been recorded in human chondrosarcoma specimens than in normal cartilage, but increasingly higher levels of MMP-2 expression stimulate the invasion and metastatic potential of chondrosarcoma cells." (PMID 34445345, 2021). "The transfection of cells with an miR-423-5p mimic significantly reduced the NGF-induced stimulation of the cell migration and MMP-2 mRNA expression in both chondrosarcoma cell lines." (PMID 34283074, 2021). "We also observed in that study a positive significant correlation between MMP-2 and NGF staining intensities of human chondrosarcoma tissue, indicating an association between the levels of these proteins and the progression of chondrosarcoma disease." (PMID 34815382, 2021). "miR-423-5p expression was negatively correlated with MMP-2 expression and the cell migratory activity in the chondrosarcoma cells." (PMID 34283074, 2021). "The pharmacological inhibitors of ERK, p38, and JNK all antagonized visfatin-mediated activities, suggesting that visfatin promotes AP-1-dependent MMP-2 production and chondrosarcoma migration through ERK, p38, and JNK signaling." (PMID 34445345, 2021). "Chemokine (C-C motif) ligand 3 (CCL3) has been found to increase MMP-2 expression in human chondrosarcoma cells and thus encourage their migratory abilities while the inhibition of MMP-2 expression abolishes this effect of CCL3." (PMID 34283074, 2021). "We enhanced miR-423-5p levels in chondrosarcoma cells by transfecting them with a specific miR-423-5p mimic, which also reduced the MMP-2 synthesis and the migratory capacity of the cells." (PMID 34283074, 2021). "The levels of NGF and MMP-2 in human chondrosarcoma tumor tissues correlated strongly with the tumor stage." (PMID 34283074, 2021). "Genetic knockdown of MMP-2 reduced the effects of visfatin upon chondrosarcoma cell migratory activity." (PMID 34445345, 2021). "Here, our results showed that NGF promoted the phosphorylation of FAK and c-Src while FAK and c-Src pharmacological inhibitors suppressed the NGF-induced promotion of MMP-2 expression and the chondrosarcoma migration." (PMID 34283074, 2021). "We found that both AP-1 inhibitors (tanshinone IIA and curcumin) inhibited visfatin-induced facilitation of MMP-2 synthesis and chondrosarcoma cell migration." (PMID 34445345, 2021). "In our previous study, NGF promoted MMP-2 expression and chondrosarcoma cell migration through the FAK and c-Src signaling cascades." (PMID 34815382, 2021). "Chemokine (C-C motif) ligand 3 enhances the migration of human chondrosarcoma cells by increasing MMP-2 expression." (PMID 33553142, 2020).
chondrosarcoma (continued). "Our previous work indicates that resistin regulates metastasis in chondrosarcoma, enhancing chondrosarcoma cell migration by increasing levels of MMP-2 expression." (PMID 30631040, 2019). "In chondrosarcomas, the expression of MMP2 has been confirmed and demonstrated a significant correlation with the tumor histological grade linking to the prognosis." (PMID 29573200, 2018). "High resistin levels in human chondrosarcoma tissues have been linked to MMP-2 expression and r-resistin promoted invasiveness and MMP-2 expression in human chondrosarcoma cells in vitro mediated by AMPK and p38 MAPK." (PMID 29361725, 2018). "In conclusion, this study showed that zaltoprofen activated PPARγ and subsequently decreased MMP2 activity in human chondrosarcoma cells, thereby contributing to anti‐tumor effects against cell viability, proliferation, migration, and invasion." (PMID 29573200, 2018). "In another study, correlation of elevated MMP-2 expression and tumor grading of chondrosarcoma was proven." (PMID 29316907, 2018). "Taken together, these results revealed that S1P inhibits cell migration by downregulation of MMP‐2 expression through upregulating TIMP‐3 expression in human chondrosarcoma cells." (PMID 28672103, 2017). "Subsequently, the S1P‐suppressed chondrosarcoma cell migratory ability and MMP‐2 expression were reversed when Src, MEK, and ERK are inhibited." (PMID 28672103, 2017). "Taken together, these results indicated that S1P inhibits human chondrosarcoma cell migration through downregulating MMP‐2 expression." (PMID 28672103, 2017). "Taken together, these results indicated that endogenous S1P suppresses miR‐101 expression, followed by augmenting TIMP‐3 induction and then preventing the MMP‐2‐dependent lung metastasis of chondrosarcoma in vivo." (PMID 28672103, 2017). "It was reported that resistin promotes chondrosarcoma metastasis and MMP2 expression through activation of AMPK/p38 signaling pathway and down-regulation of miR-519d expression in mouse models." (PMID 26729407, 2016). "In contrast, MMP2 was identified as the prominent matrix metalloproteinase in the angiogenic nodules in a rat chondrosarcoma model." (PMID 26979530, 2016). "MMP-2, in particular, has been shown to be required for switching the tumour from pre-angiogenic to angiogenic phenotype in chondrosarcomas." (PMID 25671640, 2015). "This study characterized the effects of resistin on MMP-2 expression in human chondrosarcoma, which is known to be responsible for subsequent increased migration and metastasis." (PMID 25404641, 2015). "Taken together, our results indicate that resistin promotes chondrosarcoma metastasis and MMP-2 expression through activation of the AMPK/p38 signaling pathway and down-regulation of miR-519d expression." (PMID 25404641, 2015). "The protein expressions of resistin and MMP-2 in chondrosarcoma patients were found to be significantly higher than in normal cartilage." (PMID 25404641, 2015). "The expression levels of resistin and MMP-2 in chondrosarcoma and normal cartilage were detected by immunohistochemical staining." (PMID 25404641, 2015). "AMPK activation has been reported to mediate chemokine (C-C motif) ligand 3-increased MMP-2 expression and chondrosarcoma metastasis." (PMID 25404641, 2015). "It was shown that suppression of MMP-2 activity by antisense oligonucleotides in chondrosarcoma cells resulted in suppression of tumor growth in a mouse host with wild-type MMP-2 through reduced angiogenesis." (PMID 24978435, 2014). "This was confirmed by the observation that PKCδ siRNA inhibited the enhancement of migration and MMP-2 expression in human chondrosarcoma cells." (PMID 23320110, 2013). "Our data suggest that CCL3 increases MMP-2 expression and subsequently promotes cell migration in human chondrosarcoma cells." (PMID 24047437, 2013).
chondrosarcoma (continued). "Based on these results, HGF appears to act through a signaling pathway, involving PI3K, Akt, and PKCδ to enhance cell motility and MMP-2 expression in human chondrosarcoma." (PMID 23320110, 2013). "In this study, we found that HGF induced MMP-2 expression and secretion in human chondrosarcoma cells." (PMID 23320110, 2013). "In this study, we observed that CCL3 increases the migration of human chondrosarcoma cells and upregulates the expression of MMP-2." (PMID 24047437, 2013). "Here, we also showed that the interaction between HGF and c-Met is very important for MMP-2 up-regulation and cell motility of human chondrosarcoma cells." (PMID 23320110, 2013). "The expression of CCL3, CCR5, and MMP-2 in chondrosarcoma specimens was significantly higher than that in normal cartilage." (PMID 24047437, 2013). "We also found that HGF increased the migration and expression of matrix metalloproteinase (MMP)-2 in human chondrosarcoma cells." (PMID 23320110, 2013). "The data therefore suggest that AMPKα1 and AMPKα2 are involved in CCL3-mediated migration activity and MMP-2 expression in chondrosarcoma." (PMID 24047437, 2013). "Taken together, our results indicated that HGF enhances migration of chondrosarcoma cells by increasing MMP-2 expression through the c-Met receptor/PI3K/Akt/PKCδ/NF-κB signal transduction pathway." (PMID 23320110, 2013). "In this study, we found that while CCL3 induced MMP-2 expression and secretion in human chondrosarcoma cells, treatment of cells with the MMP-2 inhibitor reduced CCL3-induced cell migration." (PMID 24047437, 2013). "Taken together, these results indicate that CCL3, CCR5, and MMP-2 expression are correlated in human chondrosarcoma specimens." (PMID 24047437, 2013). "Other studies on Huh7 cells and chondrosarcoma cells have also revealed a similar molecular mechanism in which CCL2 regulates MMP2 and MMP9 expression through the PI3K/Akt and NF-κB signaling pathways." (PMID 23941552, 2013). "Taken together, our results indicate that CCL3 enhances the migratory ability of human chondrosarcoma cells by increasing MMP-2 expression via the CCR5, AMPK, p38, and NF-κB pathways." (PMID 24047437, 2013). "We also used western blotting to confirm the results from immunohistochemistry that the expression of CCL3 and MMP-2 in chondrosarcoma was also significantly higher than that in chondrocytes." (PMID 24047437, 2013). "Here, we found that CCL3 induced MMP-2 expression and subsequently promoted migration in human chondrosarcoma through activation of the CCR5 receptor, AMPK, p38, and NF-κB signaling pathways." (PMID 24047437, 2013). "Here we show that HGF increases migration and up-regulates MMP-2 expression in human chondrosarcoma cells." (PMID 23320110, 2013). "Here, we found that CCL3 increased cellular migration and expression of matrix metalloproteinase (MMP)-2 in human chondrosarcoma cells." (PMID 24047437, 2013). "Widespread positivity for matrix metalloproteinase 2 (MMP2) have been shown in some reported cases of clear cell chondrosarcoma with aggressive clinical behavior." (PMID 22520362, 2012). "Interestingly, the evidence suggests that suppressing miR-101 and MMP-2 expression in human chondrosarcoma cells inhibits chondrosarcoma metastasis to the lungs." (PMID 34283074, 2021). "MMP-2 has been reported to control the migration and metastasis of chondrosarcomas." (PMID 34283074, 2021). "Interestingly, microtubule depolymerizing drugs display antitumor activities in soft tissue sarcomas while the transcription factor ETV5 reportedly regulates MMP-2 expression in human chondrosarcomas." (PMID 34283074, 2021). "Thus, inhibiting MMP-2 expression would likely be a useful means of preventing chondrosarcoma metastasis." (PMID 34445345, 2021). "MMP-2 reportedly regulates the invasion and metastasis of chondrosarcoma cells." (PMID 34445345, 2021).
chondrosarcoma (continued). "It therefore seems reasonable to speculate that inhibiting MMP-2 expression would be a useful therapeutic tactic in chondrosarcoma metastasis." (PMID 34283074, 2021). "Moreover, the anti-inflammatory drug zaltoprofen inhibits the proliferation, migration and invasion of chondrosarcoma cells by reducing the MMP-2 activity." (PMID 34283074, 2021). "In addition, we found that mRNA expression and protein synthesis of MMP-2, as well as wound healing and cell migration ability, were similar when we treated chondrosarcoma cells with visfatin 50 or 100 ng/mL, so we chose 50 ng/mL in all further experiments." (PMID 34445345, 2021). "In our previous experiments, we used an established orthotopic mouse model of chondrosarcoma lung metastasis to examine the stimulatory effects of NGF in metastatic chondrosarcoma, which confirmed that NGF promotes chondrosarcoma metastasis in mouse lungs by stimulating MMP-2 expression." (PMID 34815382, 2021). "Notably, chemokine (C-C motif) ligand 3 (CCL3)-facilitated increases in MMP-2 synthesis in chondrosarcoma cells encourage their migratory abilities, while inhibition of MMP-2 expression abolishes this effect of CCL3." (PMID 34445345, 2021). "The purpose of this study was to assess the anti‐tumor effects of zaltoprofen via regulation of MMP2 and PPARγ activity, and examine whether zaltoprofen could be a novel therapeutic agent in human chondrosarcoma." (PMID 29573200, 2018). "Especially in high grade central chondrosarcomas increased MMP-2 levels have been documented." (PMID 29361725, 2018). "As demonstrated by the transwell, immunoblotting, and real‐time PCR analyses, we found that S1P inhibited cell migration and MMP‐2 expression through the upregulation of the tissue inhibitor of metalloproteinase‐3 (TIMP‐3) expression in human chondrosarcoma cells." (PMID 28672103, 2017). "Moreover, CCL3 enhances cell migration and metastasis by up-regulating matrix metalloproteinase-2 (MMP)-2 expression in chondrosarcoma cells." (PMID 26713602, 2016). "Previous studies have reported significant overexpression of MMP-2 in human chondrosarcoma cells." (PMID 25404641, 2015). "It has been reported that MMP-2 inhibition suppressed migration and metastasis of chondrosarcoma." (PMID 25404641, 2015). "Moreover, treatment with resistin increased matrix metalloproteinase (MMP)-2 expression and promoted cell migration in human chondrosarcoma cells." (PMID 25404641, 2015). "Of these MMPs, MMP-2 has been reported to modulate the metastasis of human chondrosarcoma." (PMID 23320110, 2013). "Therefore, blocking CCR5 reduced CCL3-mediated cell migration and MMP-2 expression in human chondrosarcoma cells." (PMID 24047437, 2013). "Whether other transcription factors are involved in HGF-induced MMP-2 expression in chondrosarcoma needs further examination." (PMID 23320110, 2013). "Therefore, the NF-κB binding site is likely to be an important site for HGF-induced MMP-2 expression and cell migration in human chondrosarcoma." (PMID 23320110, 2013). "Therefore, an interaction between HGF and c-Met appears to be very important for cell migration and MMP-2 expression in human chondrosarcoma." (PMID 23320110, 2013). "Furthermore, the expression levels of CCL3, CCR5, and MMP-2 were correlated in human chondrosarcoma specimens." (PMID 24047437, 2013). "We also established cells expressing HGF-shRNA to confirm whether HGF mediated cell migration and MMP-2 expression in human chondrosarcoma cells." (PMID 23320110, 2013). "We then examined whether MMP-2 played a role in NGF-regulated migration in a chondrosarcoma." (PMID 34283074, 2021). "However, in OUMS27shPPAR and SW1353shPPAR cells, the downregulation of MMP2 activities by zaltoprofen was inhibited by PPARγ silencing, thus, suggesting that a zaltoprofen‐induced PPARγ activation could reduce MMP2 activities in chondrosarcoma cells." (PMID 29573200, 2018).